MIR4759 (microRNA 4759)
Synonyms: hsa-mir-4759
Gene: MicroRNA gene on chromosome 21 (26,953,961 to 26,954,043, forward strand). Ensembl gene ENSG00000266133.
Homologues: Orthologues: chimpanzee MIR4759 (100% identical).